HIPK2 (homeodomain interacting protein kinase 2)
Diseases named in the same sentence as HIPK2 in open-access papers (continued):
Sharing a sentence is not in itself a finding about the gene and the disease.
glioma (3 papers, 2016 to 2024). A benign or malignant brain and spinal cord tumor that arises from glial cells (astrocytes, oligodendrocytes, ependymal cells). "However, the functional role and underlying mechanism of SMOC1, HIPK2, UBA52, S100A6, PPP1CB, CALD1, and TMSB4X in the occurrence and development of diffuse high-grade gliomas was still unknown." (PMID 39530009, 2024). "Apart from its impacts on ATM and HIPK2, ClQ also affects the abundance of anti-apoptotic kinase AKT in company with inhibiting autophagy, a condition that induces death in non-stem glioma cells." (PMID 37174691, 2023).
keloid (3 papers, 2023 to 2025). An irregularly shaped, elevated mark on the skin caused by deposits of excessive amounts of collagen during wound healing. "ZC3H13 overexpression increased m6A modification of HIPK2 mRNA, leading to heightened mRNA stability and elevated HIPK2 expression in keloid tissues." (PMID 39472463, 2024). "In a model of primary normal skin and keloid HIPK2, it has been found overexpressed in keloid-derived keratinocytes compared to normal keratinocytes." (PMID 36831402, 2023). "Therefore, ZC3H13-mediated HIPK2 mRNA m6A modification could promote keloid progression by the post-transcriptional regulation of HIPK2." (PMID 39472463, 2024). "HIPK2 inhibition by small-interfering (si) RNA abrogates the EMT markers and Smad3 phosphorylation, becoming a potential pharmacologic target for anti-keloid therapy." (PMID 36831402, 2023).
myelodysplastic syndrome (3 papers, 2011 to 2022). A clonal hematopoietic disorder characterized by dysplasia and ineffective hematopoiesis in one or more of the hematopoietic cell lines. "Mutations of HIPK2 (R868W and N958I) impairing its ability to activate AML1 have been identified in both AML- and Myelodysplastic Syndrome (MDS)-suffering patients." (PMID 31405039, 2019).
nasopharyngeal carcinoma (3 papers, 2020 to 2023). A carcinoma arising from the nasopharyngeal epithelium. "Spen family transcriptional repressors activate PI3K/AKT signaling to modulate the c-JUN/miR-4652-3p/HIPK2 axis, thereby activating epithelial-mesenchymal transition signaling and promoting nasopharyngeal carcinoma metastasis." (PMID 37925170, 2023). "In that study, the authors found that the oncogene SPEN induces miR-4652-3p expression in nasopharyngeal carcinoma (NPC) by activation of the PI3K/AKT/c-JUN signaling and that miR-4652-3p targets and downregulates HIPK2." (PMID 36900356, 2023).
neuroblastoma (3 papers, 2012). Neuroblastoma (NB) is the most common solid, extracranial childhood tumor. "Thus, MYCN sensitizes neuroblastoma cells to apoptosis by upregulation of the HIPK2/p53Ser46 pathway via ATM-dependent DNA damage response (DDR) that activates HIPK2." (PMID 22889244, 2012). "HIPK2 is largely expressed in human primary MYCN amplification (MNA) neuroblastoma tissues and its expression is induced by MYCN, whose inactivation inhibits HIPK2 and impairs p53Ser46 phosphorylation and apoptosis." (PMID 22889244, 2012).
non-small cell lung carcinoma (3 papers, 2021 to 2023). A group of at least three distinct histological types of lung cancer, including non-small cell squamous cell carcinoma, adenocarcinoma, and large cell carcinoma. "ExomiR-1260b, derived from non-small cell lung cancer (NSCLC) has been shown to target HIPK2 in human umbilical endothelial cells (HUVECs) and promote the angiogenesis, migration, invasion, and chemoresistance of NSCLC cells." (PMID 37345014, 2023).
papillary thyroid carcinomas (3 papers, 2011 to 2017). "HIPK2 is undetectable in 91.7% of papillary thyroid carcinomas and in 60.0% of follicular thyroid carcinomas, compared with its overexpression in benign nodular hyperplasia." (PMID 28607924, 2017). "Conversely, HIPK2 was undetectable in 91.7% of papillary thyroid carcinomas (PTCs) and in 60.0% of follicular thyroid carcinomas (FTCs)." (PMID 21698151, 2011).
respiratory failure (3 papers, 2019 to 2023). The significant impairment of gas exchange within the lungs resulting in hypoxia, hypercarbia, or both, to the extent that organ tissue perfusion is severely compromised. "According to these results, the proper expression of surfactant genes requires in vivo the presence of both the HMGA1 and HIPK2 proteins, and their lack mainly accounts for the atelectasis condition with a respiratory failure of DKO mice at birth." (PMID 31582725, 2019). "About 50% of these Hmga1/Hipk2 double knock-out (DKO) mice die within 12 h of life (P1) for respiratory failure." (PMID 31582725, 2019). "We have previously demonstrated that Hipk2-null (Hipk2-KO) mice present cerebellar alterations associated with psychomotor abnormalities and that the double ablation of HIPK2 and its interactor HMGA1 causes perinatal death due to respiratory failure." (PMID 34361060, 2021). "Here, we report that Hmga1/Hipk2 DKO mice die within 12 h of life for respiratory failure, likely owing to impaired lung development associated to a drastic reduction in surfactant proteins, whose expression is positively regulated by both HMGA1 and HIPK2." (PMID 31582725, 2019).
skin cancer (3 papers, 2011 to 2021). "Mice lacking HIPK2 expression fastly developed skin cancer using the two step skin carcinogenesis protocol indicating that HIPK2 is a tumor suppressor gene and involved in cutaneous SCC." (PMID 22110707, 2011).
thymoma (3 papers, 2021 to 2023). A neoplasm arising from the epithelial cells of the thymus. "In thymomas, we found that SOX9 expression was positively correlated with the expression of HIPK2, which is a critical transcriptional factor determining thymic tuft cells development and shaping thymic function." (PMID 34778027, 2021). "Furthermore, HIPK2, HDAC9, and FEZF2 displayed a significantly higher expression in thymic carcinomas than in thymomas in both datasets." (PMID 38201543, 2023).
Ataxia (2 papers, 2015 to 2023). Ataxia refers to impaired coordination of voluntary muscle movement. "In particular, we found that Hipk2 genetic ablation has a causative role in ataxia-like cerebellar disorders." (PMID 26633710, 2015). "A potential role of Hipk2 in cerebellar homeostasis and ataxia emerged from the behavioral and morphological analysis of Hipk2-KO mice." (PMID 36935052, 2023). "Finally, having provided support to the hypothesis that cerebellar dysfunction is associated with Hipk2 loss in Purkinje cells, this study raises the possibility that Hipk2 may be considered a potential therapeutic target for treating some forms of cerebellar ataxia." (PMID 26633710, 2015). "On the other hand, we cannot rule out the possibility that among the numerous kinds of cerebellar ataxia sharing similar molecular mechanisms, others also can be linked to Hipk2." (PMID 26633710, 2015). "Moreover, HIPK2 is one of the genes whose expression has been found to be altered in peripheral blood mononuclear cells isolated from patients affected by Friedrich's ataxia, further suggesting HIPK2 as a novel gene involved in ataxia-like cerebellar disorders." (PMID 36935052, 2023). "Our results seem to suggest that some forms of cerebellar disorders might be partly because of the lack of Hipk2 and candidate Hipk2 as a novel gene involved in the pathogenesis of some forms of ataxia-like cerebellar disorders." (PMID 26633710, 2015).
brain cancer (2 papers, 2014 to 2023). A primary or metastatic malignant neoplasm affecting the brain. "The kinase CSNK1E had been previously associated only with non-brain cancers, while HIPK2, LYN, and EPHB4 have been suggested as targets for anti-tumor therapies." (PMID 25236784, 2014).
cognition impairment (2 papers, 2020 to 2022). "Therefore, inhibition of the HIPK2/JNK/c-Jun signaling pathway has specific guiding significance for treating neonatal brain neurotoxicity and cognitive impairment, and it can be used as a potential target to treat general anesthetic-induced neurotoxicity and cognitive impairment." (PMID 36504660, 2022).
depression (2 papers, 2019 to 2023). "Given the correlation between circular RNA HIPK2 (circHIPK2) and depression and the observation that the level of circHIPK2 expression was significantly increased in CUS-treated mice compared with that in the control group, further experiments were performed." (PMID 31439031, 2019).
endotoxemia (2 papers, 2022 to 2024). "In addition, overexpression of HIPK2 alleviates LPS-induced inflammation in macrophages, and HIPK2-KO mice are more susceptible to LPS-stimulated endotoxemia." (PMID 36362432, 2022). "The HDAC3 inhibitors protected wild-type or Hipk2 BMs-reconstituted mice from LPS-induced endotoxemia." (PMID 39040100, 2024).
fibrosis (2 papers, 2021 to 2022). the formation of excess fibrous connective tissue in an organ or tissue in a reparative or reactive process. "Post-mortem examination and histological analysis revealed that Hipk2 loss causes neuronal alterations throughout the central nervous system (CNS), a myopathic phenotype, and cardiac fibrosis associated with increased cardiomyocyte size." (PMID 34361060, 2021).
ischaemic stroke (2 papers, 2021 to 2022). "Given our previous study that Nrf2 inhibits the inflammatory cascade caused by the NLRP3 inflammasome, thereby alleviating cerebral I/R injury in Sprague–Dawley (SD) rats, the effect of HIPK2 on inflammation in ischemic stroke is worthy of inquiry." (PMID 36362432, 2022). "The suppression of circ HIPK2 regulates function recovery after ischaemic stroke in NSCs." (PMID 33579365, 2021). "Despite the specific interaction between FBXO3 and HIPK2 requiring further study, we believe that our data suggest the therapeutic relevance of FBXO3 to ischemic stroke and provide a new perspective on the mechanism of I/R injury." (PMID 36362432, 2022).
ischemic cardiomyopathy (2 papers, 2021 to 2023). Ischemic cardiomyopathy is a cardiomyopathy in which a weakness in the muscle of the heart due to inadequate oxygen delivery to the myocardium with coronary artery disease being the most common cause. "Alternatively, HIPK2 was found reduced in human end-stage ischemic cardiomyopathy." (PMID 36831402, 2023).
Lafora disease (2 papers, 2020 to 2023). Lafora disease (LD) is a rare, inherited, severe, progressive myoclonic epilepsy characterized by myoclonus and/or generalized seizures, visual hallucinations (partial occipital seizures), and progressive neurological decline. "Several data suggest that HIPK2 may be a potential biomarker and/or even a new putative therapeutic target for neurological diseases, such as ASDs, Lafora disease, HSP, RETT and ENS pathologies." (PMID 36935052, 2023).
leukemia (2 papers, 2015 to 2023). A malignant (clonal) hematologic disorder, involving hematopoietic stem cells and characterized by the presence of primitive or atypical myeloid or lymphoid cells in the bone marrow and the blood. "In contrast, the leukemia-associated fusion protein PML-RARα induces the degradation of HIPK2 by inhibiting PML stabilization of HIPK2, underscoring a novel mechanism in the regulation of leukemogenesis." (PMID 37345014, 2023).
Liver fibrosis (2 papers, 2022 to 2023). "The inhibition of HIPK2 reduces the expression of mesenchymal markers and Smad3 phosphorylation, suggesting the potential involvement of HIPK2 in liver fibrosis." (PMID 36831402, 2023). "Liver fibrosis is also mediated by HIPK2 activation in hepatic stellate cells." (PMID 36172184, 2022). "In agreement, there is an interesting link between liver fibrosis, SIRT6 and HIPK2." (PMID 36831402, 2023).
radiation pneumonitis (2 papers, 2020 to 2023). Inflammation of the lung due to harmful effects of ionizing or non-ionizing radiation. "In this study, we aimed to evaluate the impact of HIPK2 gene variant on risk of radiation pneumonitis for patients with pulmonary malignancies." (PMID 31915028, 2020).
renal carcinoma (2 papers, 2020 to 2021). A carcinoma arising from the epithelium of the renal parenchyma or the renal pelvis. "In our study, HIPK2 did not have a significant difference in renal cancer tissues, but its low expression predicted a poor prognosis, and the univariate analysis and multivariate analysis also indicates that low expression may be an independent prognostic marker for ccRCC." (PMID 33495417, 2021).
thyroid tumor (2 papers, 2011 to 2017). A benign or malignant neoplasm affecting the thyroid gland.
tonsillar squamous cell carcinoma (2 papers, 2017 to 2022). A squamous cell carcinoma that arises from the mucosal lining of the tonsil and tends to metastasize early to the lymph nodes. "In tonsillar squamous cell carcinoma, HIPK2 overexpression was associated with shorter overall survival and disease-free survival." (PMID 36289359, 2022).
breast ductal carcinomas (1 paper, 2012). "On the other hand, breast ductal carcinomas with high HMGA1 expression and with low apoptotic index (not shown) show HIPK2 cytoplasmic localization, meaning likely HIPK2 inactivation." (PMID 22889244, 2012). "Thus, immunostaining of breast ductal carcinomas with low HMGA1 expression and with high apoptotic index (not shown) results in HIPK2 nuclear localization." (PMID 22889244, 2012).
Encephalopathy (1 paper, 2023). Encephalopathy is a term that means brain disease, damage, or malfunction. "GTP2 is linked to neurological disease, encephalopathy, and microcephaly, and HIPK2 is associated with tumor progression, and malignant neoplasm." (PMID 37949935, 2023).
epilepsy (1 paper, 2025). A brain disorder characterized by episodes of abnormally increased neuronal discharge resulting in transient episodes of sensory or motor neurological dysfunction, or psychic dysfunction. "We identified three methylation biomarkers (IL1RAP, HIPK2 and CNMD) and validated their utility in differentiating FCD IIa from IIb in a larger replication study and an independent cohort of patients with epilepsy." (PMID 40860011, 2025).
Familial adenomatous polyposis (1 paper, 2023). Familial adenomatous polyposis (FAP) is characterized by the development of hundreds to thousands of adenomas in the rectum and colon during the second decade of life. "Thus, HIPK2 silencing increases the xenograft tumor growth and the physiologic relevance was assessed by analyzing the HIPK2 gene expression in human specimens collected from patients with the familial adenomatous polyposis (FAP) and with sporadic colorectal cancer (CRC)." (PMID 36900356, 2023).
gestational hypertension (1 paper, 2023). "HIPK2 has been shown to play a role in angiogenesis of a model of gestational hypertension induced by hypoxia and reoxygenation (H/R)." (PMID 36900356, 2023).
Glucose intolerance (1 paper, 2023). Glucose intolerance (GI) can be defined as dysglycemia that comprises both prediabetes and diabetes. "Alas1 is associated with glucose intolerance in skeletal muscle and Hipk2 is associated with cell proliferation and inflammation in skeletal muscle." (PMID 37012297, 2023).
hearing loss (1 paper, 2022). "Other genes were related to BPD-associated outcomes such as retinopathy of prematurity (ROP, e.g., GBP3, FJX1, HIPK2) and hearing loss (e.g., GJB6, TMEM63B) and mitochondrial energy metabolism (e.g., TOMM7, SLC25A26, SLC25A33, PDK1, PKM, MDH1)." (PMID 35484630, 2022).
heart failure (1 paper, 2023). Inability of the heart to pump blood at an adequate rate to meet tissue metabolic requirements. "The authors found that adenovirus-mediated HIPK2 overexpression downregulates heart failure markers, concluding that HIPK2 is a key molecule to maintain basal cardiac function." (PMID 36831402, 2023).
hereditary spastic paraplegia (1 paper, 2020). Hereditary spastic paraplegias (HSP) comprise a genetically and clinically heterogeneous group of neurodegenerative disorders characterized by progressive spasticity and hyperreflexia of the lower limbs. "The balance between HIPK2-mediated phosphorylation and neddylation-dependent degradation controls spastin protein levels, revealing novel therapeutic targets for hereditary spastic paraplegia." (PMID 33106322, 2020).
invasive ductal adenocarcinomas (1 paper, 2015). "Immunohistochemical analyses were performed by using anti-HIPK2 specific antibody (Ab) in TMAs that included normal pancreatic tissue, PanIN-3, and invasive ductal adenocarcinomas." (PMID 25868975, 2015).
lipoma (1 paper, 2021). A benign, usually painless, well-circumscribed lipomatous tumor composed of adipose tissue. "We detected an upregulation of senescence markers p21 and HIPK2 but not CDKN2B (p15) in high-passage compared with low-passage cells from lipomas of patients with PHTS (LipPD1)." (PMID 34273354, 2021).
lung adenocarcinoma (1 paper, 2025). A carcinoma that arises from the lung and is characterized by the presence of malignant glandular epithelial cells.
lupus nephritis (1 paper, 2023). Glomerulonephritis in the context of systemic lupus erythematosus. "Additionally, for ‘response to cyclophosphamide in systemic lupus erythematosus with lupus nephritis’ (12 genes in GWAS), we found two overlap genes, BARX2 and HIPK2." (PMID 37048133, 2023).
lymph node metastasis (1 paper, 2014). "Correlation analysis showed that HIPK2 expression was closely associated with Dukes staging and infiltration degrees, but not to sex, age, degree of differentiation, or lymph node metastasis." (PMID 25282590, 2014).
motor neuron disease (1 paper, 2024). "Reducing HIPK2 activity improves phenotypes in mouse models of motor neuron disease ALS and IL6 levels, and the splicing of Fnip1 is altered in ALS conditions." (PMID 39337533, 2024).
pancreatic adenocarcinoma (1 paper, 2015). "Consistently, we found a progressive reduction of HIPK2 expression in the increasingly malignant stages of pancreatic adenocarcinomas." (PMID 25868975, 2015). "In this study, we found for the first time that HIPK2 was under-expressed in PanIN-3 and in pancreatic adenocarcinoma in contrast to the high expression levels observed in normal pancreas." (PMID 25868975, 2015). "We found that the percentage of HIPK2 positive cells, irrespective of the intensity of the staining, was significantly reduced in PanIN-3 and in pancreatic adenocarcinoma compared to normal tissue." (PMID 25868975, 2015).
renal tumors (1 paper, 2022). "In silico analysis showed that tRF-5b can regulate the activity of the NFIC, GNAO1 and HIPK2 proteins, which are associated with renal tumors." (PMID 35409004, 2022).